PES1 (pescadillo ribosomal biogenesis factor 1)
Diseases named in the same sentence as PES1 in open-access papers (continued):
Sharing a sentence is not in itself a finding about the gene and the disease.
cancer (18 papers, 2012 to 2024). A tumor composed of atypical neoplastic, often pleomorphic cells that invade other tissues. "As a nucleolar protein associated with ribosome biogenesis in multiple cancer types, PES1 has been reported to be overexpressed, promoting cancer cell proliferation and invasion." (PMID 37076985, 2023). "Several studies have explored the molecular mechanisms underlying the abnormal expression of PES1 during tumour progression in human cancers." (PMID 36217758, 2023). "PES1 is associated with tumor growth and drug resistance, and served as a potential cancer marker for diagnosis and a putative therapeutic target for HNSCC." (PMID 36217758, 2023). "Our findings suggest that PES1 is associated with tumour growth and drug resistance and served as a potential cancer marker for diagnosis and a putative therapeutic target for HNSCC." (PMID 36217758, 2023). "We show that knockdown of the ribosomopathy factor SBDS, or of key ribosome biogenesis factors (PPAN, NPM, PES1) is associated with enhanced levels of ATG7 in cancer cells." (PMID 34944838, 2021). "As a nucleolar protein associated with ribosome biogenesis, pescadillo homolog 1 (PES1) has been reported to participate in the development of many cancers." (PMID 32448371, 2020). "High PES1 expression is associated with the worse overall and relapse-free survival of patients with malignant tumor." (PMID 30705367, 2019). "More and more research have shown that PES1 is closely associated with tumorgenesis via improving cell proliferation and participating in the progress of cell cycle in cancer cells." (PMID 27409667, 2016). "Some studies have also shown that PES1 is associated with the prognosis of some cancers." (PMID 37076985, 2023). "Abnormally expressed PES1 is associated with poor prognosis in these cancers." (PMID 31718704, 2019). "A comparison of gene expression profiles of FACS-sorted double positive keratinocytes isolated from UV-treated WT and TG mice indicated increased expression of Pes1, Rad21, Tfdp1, and Cks1b genes in TG mice linked to cell transformation, invasion, and metastasis of cancer cells." (PMID 23738074, 2013). "Recently, deregulated expression of PES1 was found to be associated with cancer development." (PMID 22860098, 2012). "It was found that PES1 expression is elevated in many cancers, including BLCA, BRCA, CHOL, COAD, ESCA, HNSCC, KIRC and LUAD." (PMID 36217758, 2023). "The results proved that the PES1 mRNA expression was upregulated in various cancer tissues than in corresponding normal tissues, including HNSCC." (PMID 37076985, 2023). "PES1 has been shown to be highly expressed in many cancer types and promote malignant behavior of tumor cells by affecting various oncogenic signaling pathways." (PMID 36959575, 2023). "Last, the results of our study suggest that PES1 is a potential cancer marker for diagnosis and a putative therapeutic target in HNSCC." (PMID 36217758, 2023). "Elevation of PES1 results in tumor cell proliferation and malignant transformation and the poor prognosis in multiple types of cancers." (PMID 36959575, 2023). "Pescadillo ribosomal biogenesis factor 1 (PES1) plays a critical role in the progression of numerous cancers." (PMID 36217758, 2023). "First, PES1 expression was compared between normal and carcinoma tissues and assessed the relationship of PES1 expression with the clinical feature of HNSCC patients." (PMID 37076985, 2023). "A series of studies has indicated that PES1 is highly expressed in a variety of tumors and plays a crucial role in promoting cancer." (PMID 34976188, 2022). "PES1, involved in the pre-ribosomal RNA processing, is an oncogene that promotes the carcinogenesis and development of different types of cancers." (PMID 35372049, 2022). "Here, we will describe the tumors related to PES1 and the molecular mechanisms of PES1 in tumors as a starting point from which to explore potential therapeutic targets for patients with malignant tumors." (PMID 34976188, 2022).
cancer (continued). "On the other hand, the repression of PES1 led to more cancer cell apoptosis after treatment with BET inhibitors." (PMID 31718704, 2019). "Highly expressed PES1 results in cancer cell proliferation and malignant transformation and the poor prognosis in multiple types of cancer." (PMID 31718704, 2019). "PES1 exhibited strong nuclear staining (brown nuclei) in cancer cells and lymph nodes, respectively." (PMID 22860098, 2012). "Previous studies have demonstrated that PES1 may serve as a potential cancer marker for diagnosis or as a putative therapeutic target in cancer treatment." (PMID 36217758, 2023). "In addition, PES1 activates Wnt/β‐Catenin signaling and stabilizes β‐Catenin in human cancer cells in a β‐Catenin‐dependent manner via siRNA‐mediated knockdown or CRISPR/Cas9 strategies." (PMID 37076985, 2023). "This means that PES1 may be a potential key biomarker of adverse consequences and a potential molecular target in cancer treatment." (PMID 34976188, 2022). "Many studies have shown that high expression of PES1 is often closely related to the occurrence, proliferation, invasion, metastasis, prognosis and sensitivity to chemotherapeutics of various human malignant tumors through a series of molecular mechanisms and signaling pathways." (PMID 34976188, 2022). "Pescadillo ribosomal biogenesis factor 1 (PES1) has been identified as a cancer-related gene." (PMID 34976188, 2022). "All these data suggest that PES1 plays an oncogenic role in various cancers." (PMID 34782005, 2021). "In addition, a recent study revealed that PES1 facilitates telomerase assembly and negatively correlates with senescence in cancer cells, suggesting that PES1 is a promising target for cancer therapy." (PMID 34782005, 2021). "The increased expression of PES1 is involved in the proliferation and malignant conversion of cells and may contribute to the occurrence and development of some human cancers such as prostate, head and neck, stomach, colon, breast and ovarian cancer." (PMID 30705367, 2019). "Overexpressed PES1 promotes carcinogenesis in various types of malignant tumors." (PMID 31718704, 2019). "Encouragingly, the knockdown of PES1 impedes cancer cell growth and apoptosis." (PMID 31718704, 2019). "Therefore, compared with JQ1 treatment alone, the knockdown of PES1 plus JQ1 treatment decreases cancer cell resistance to JQ1 in PANC-1 cells." (PMID 31718704, 2019). "Overall, these data indicated that wild-type PES1 could promote the growth of cancer cells in vitro and in vivo." (PMID 27409667, 2016). "IHC staining results showed that in the cancer tissues of 59 patients with GC, PES1 was highly expressed in 24 tissues, while no positive staining was detected in the corresponding normal tissues adjacent to the cancer." (PMID 34976188, 2022). "Subsequently, human cancer cell lines were found to express the homologous gene, PES1, at elevated levels and PES1 overexpression induced transformation of non-tumorogenic fibroblast cell lines, thus raising the possibility that Pes proteins promote cell proliferation." (PMID 22384214, 2012).
tumor (18 papers, 2012 to 2024). "GSVA showed that among tumor immunological pathways, PES1 was negatively associated with multiple immune‐related pathways, such as NK cell‐mediated cytotoxicity, T‐cell receptors, B‐cell receptors, and Toll‐like receptor signaling pathways." (PMID 37076985, 2023). "As a nuclear protein encoder, PES1 is involved in tumour progression, cell senescence, cell cycle regulation, DNA replication and ribosome biogenesis." (PMID 36217758, 2023). "The results indicated that compared with sh-NC treatment, sh-PES1 treatment caused reduced PES1 mRNA expression as well as decreased tumor growth and tumor volume (p < 0.05)." (PMID 32448371, 2020). "Furthermore, tumor‐infiltrating immune cells and antitumor drug susceptibility were negatively related to PES1 expression." (PMID 37076985, 2023). "Interestingly, pathways associated with tumor growth are also present in the PES1 high‐expression group." (PMID 37076985, 2023). "Thus, as a novel diagnostic and prognostic biomarker, PES1 promotes tumour progression in HNSCC." (PMID 36217758, 2023). "As an important tumour‐promoting factor, PES1 plays an important role in tumour development and progression." (PMID 36217758, 2023). "Here, we established a subcutaneous tumor model using murine ESCC cells with PES1 knockdown and observed that PES1 knockdown increased the infiltration of CD8+ T cells into the ESCC subcutaneous tumors." (PMID 36959575, 2023). "The results indicated that the mRNA level of PES1 was significantly higher in ESCC tissues than that in non-tumor tissues, which was consistent with the analysis on public databases." (PMID 36959575, 2023). "The effects of PES1 on cell proliferation and tumour growth in HNSCC were elevated by colony formation, CCK8 assays and tumorigenicity assay in nude mice." (PMID 36217758, 2023). "Similar to the results in the HPV‐negative group, PES1 was highly expressed in HPV‐positive tumour tissues." (PMID 36217758, 2023). "In a word, PES1 can promote tumor invasion and lymphangiogenesis by regulating the expression of HIF-1α." (PMID 34976188, 2022). "Mechanistically, SNHG17 interacts with PES1 to inhibit the Trim23-mediated ubiquitination of PES1, resulting in increased PES1 stability and enhanced tumor growth and metastasis." (PMID 34782005, 2021). "The results indicated that tumor tissues showed increased PES1 and FOSL2 expression compared with NCTs." (PMID 34782005, 2021). "In addition, the protein level of IL15 and the IL15 secretion were also increased in KYSE150 and AKR cells with PES1 knockdown, which was further confirmed in subcutaneous tumor samples via western blotting." (PMID 36959575, 2023). "We further validated the tumour‐promoting effects of PES1 in HNSCC cells." (PMID 36217758, 2023). "Finally, we used cell function assays to explore if PES1 influences tumor growth and metastasis in HNSCC." (PMID 37076985, 2023). "Since PES1 was negatively correlated with CD8+ CTL infiltration, we explored whether PES1 was involved in the regulation on the tumor immune response." (PMID 36959575, 2023). "Only PES1 knockdown decreased tumor volume and weight by 72% and 85% (vs. SCR), respectively." (PMID 36959575, 2023). "Moreover, the expression levels of Ki‐67 (a key indicator of cell growth) were clearly reduced in tumour tissues with the deletion of PES1." (PMID 36217758, 2023). "Western blotting confirmed the knockdown effect of PES1 in subcutaneous tumor masses." (PMID 36959575, 2023). "Furthermore, PES1 expression increased in tumor stage and pathological grade groups among the HNSCC cases." (PMID 37076985, 2023). "Moreover, our study reveals that PES1 plays an essential role in the tumour immune microenvironment." (PMID 36217758, 2023).
tumor (continued). "PES1 has been found to play an indispensable role in cell proliferation and may be involved in the process of oncogenic transformation and tumor progression." (PMID 34976188, 2022). "In addition, PES1 silencing resulted in a decrease in PES1 mRNA expression in mice, as well as a decrease in tumor size (p <0.05)." (PMID 34976188, 2022). "In addition to sugar metabolism and the cell replication cycle 29, highly expressed PES1 promotes tumor occurrence and progression by promoting tumor cell proliferation, invasion and migration." (PMID 34976188, 2022). "Collectively, we found that SNHG17 exerts tumor-promoting functions through PES1 and FOSL2." (PMID 34782005, 2021). "In addition, PES1 can increase the expression of tumor-promoting ERα and decrease the expression of tumor-suppressive ERβ." (PMID 33968766, 2021). "Similarly, PES1 protein has been demonstrated to play a key role in oncogenic transformation and tumor progression." (PMID 34830469, 2021). "However, whether PES1 can remodel the tumor microenvironment to affect ICB efficacy remains to be determined." (PMID 36959575, 2023). "In addition, we found that PES1 plays an essential role in the tumour immune microenvironment." (PMID 36217758, 2023). "However, PES1, ERα and ERβ protein levels were significantly correlated with tumor size (P = 0.005, 0.003, 0.007), ETE (P = 0.002, 0.001, 0.003), LNM (P = 0.004, 0.006, 0.003), BRAFV600E mutation (P = 0.008, 0.002, 0.004) and TNM stage (P = 0.002, 0.001, 0.002)." (PMID 30705367, 2019). "Silencing of PES1 led to a reduction in HNSCC cell proliferation and tumour growth and increased HNSCC cell sensitivity to cisplatin." (PMID 36217758, 2023). "In follow‐up experiments, we knocked down PES1 in HNSCC cells with high PES1 expression and found that silencing of PES1 led to a reduction in HNSCC cell proliferation and tumour growth." (PMID 36217758, 2023). "Knockdown of PES1 remarkably reduced the growth of AKR subcutaneous tumors in vivo as indicated by the measurement on tumor volume and tumor weight." (PMID 36959575, 2023). "Increased PES1 and ERα protein levels and decreased ERβ protein level were correlated with the aggressive behaviors of PTC patients such as large tumor size, ETE, LNM, high BRAFV600E expression and high TNM stage." (PMID 30705367, 2019). "Interestingly, most CIDGS-related genes, such as XRCC6, ST13, PES1, EFHD2, APOL2, ACTR2, and CDCP1, were markedly upregulated in HNSCC tumor samples, whereas several other genes, such as MARCO, MRC1, and CD83, were upregulated in healthy samples." (PMID 38666027, 2024). "Additionally, increased protein levels of PES1 were observed in ESCC samples by immunohistochemistry (IHC) in 60 pairs of paraffin ESCC samples and matched non-tumor tissues (Cohort-60)." (PMID 36959575, 2023). "Silencing of PES1 reduces HNSCC cell proliferation and tumour growth." (PMID 36217758, 2023). "In summary, PES1 promotes HNSCC cell proliferation and tumour growth in vivo and in vitro." (PMID 36217758, 2023). "PES1 knockdown significantly reduced HNSCC cell proliferation and tumour growth." (PMID 36217758, 2023). "As expected, PES1 knockdown dramatically enhanced the infiltration of CD8+ CTL in AKR subcutaneous tumors and also increased the percentages of GZMB+/CD8+ CTL, a marker of activated CD8+ CTL, in tumor microenvironment compared to SCR group." (PMID 36959575, 2023). "In addition, we compared the differences in PES1 expression levels in HPV‐negative cancer and normal tissues, and the results showed that PES1 was highly expressed in tumour tissues." (PMID 36217758, 2023). "Increased PES1 and ERα protein levels and decreased ERβ protein level were correlated with the aggressive behaviors of PTC patients such as large tumor size, extrathyroidal extension (ETE), lymph node metastasis (LNM), high BRAFV600E expression and high TNM stage." (PMID 30705367, 2019). "However, with IL15 knockdown and PES1 knockdown have no reduction in tumor volume and weight." (PMID 36959575, 2023).
tumor (continued). "We also examined the protein expression of PES1 in another 12 pairs of fresh ESCC tissues and matched non-tumor tissues and proved that the protein level of PES1 was dramatically upregulated in ESCC samples compared with their non-tumor counterparts." (PMID 36959575, 2023).
infection (2 papers, 2022 to 2024). The state of being infected such as from the introduction of a foreign agent such as serum, vaccine, antigenic substance or organism. "PES1 also shows some function for dissemination during in vivo infection." (PMID 36503341, 2022). "Both the overexpression and depletion of PES1 resulted in decreased mortality during infection." (PMID 36503341, 2022).
psychiatric disorder (1 paper, 2025). A disorder characterized by behavioral and/or psychological abnormalities, often accompanied by physical symptoms. "Several genes, such as PES1, SPI1, and NSF, exhibit multiple significant associations across different traits, indicating their potential central roles in the genetic network influencing psychiatric disorders." (PMID 39905509, 2025).
PES1 also shares sentences with these, for which no sentence is quoted: papillary thyroid cancer (2 papers); bladder urothelial carcinoma (1); breast invasive carcinoma (1); cholangiocarcinoma (1); colorectal (1); depression (1); glioblastoma (1); Heat Stroke (1); Hypertension (1); infarction (1); lung adenocarcinoma (1); malaria (1); melanoma (1); microcephaly (1); oligodendroglioma (1); thyroid cancer (1).